ACE (angiotensin I converting enzyme)
Diseases named in the same sentence as ACE in open-access papers (continued):
Sharing a sentence is not in itself a finding about the gene and the disease.
COVID-19 (continued). "Results showed that the ACE-DD genotype of ACE2, (GSTM1+/+) (GSTT1−/−) genotype of GST gene, and CA genotype (heterozygosity) of miR-423 rs6505162 genes, which were found in the patient, could be independent risk factors of severe COVID-19, even without comorbidities." (PMID 35371838, 2022). "To date, the actual impact of ACE inhibitor and ARB prescriptions on COVID-19 patients has not been assessed in current studies." (PMID 34490373, 2021). "Unlike ACE inhibitors that enhance the expression of ACE2, carvedilol reduces its expression, therefore, this drug can be useful for all COVID-19 patients." (PMID 33244381, 2020). "Angiotensin converting enzyme (ACE) inhibitors or angiotensin receptor blockers (ARBs), which were initially blamed for the poor outcome of the disease, do not affect the clinical outcome of patients with COVID-19." (PMID 39051337, 2024). "Using mass spectrometry, we assessed key metabolites of the classical RAS (angiotensins I–II) and alt-RAS (angiotensins 1–7 and 1–5) pathways as well as ACE and ACE2 concentrations in 159 patients hospitalized with COVID-19, stratified by disease severity (severe, n = 76; non-severe: n = 83)." (PMID 36418458, 2022). "The majority of these studies provided evidence that angiotensin converting enzyme (ACE) inhibitors and angiotensin-receptor blockers (ARBs) do not adversely affect the COVID-19 progression or may even be beneficial." (PMID 36145576, 2022). "However, patients receiving angiotensin II receptor blockers and ACE inhibitors, widely used antihypertensives that increase ACE2 expression, showed a lower COVID-19 mortality rate compared to patients not receiving these antihypertensives." (PMID 34858409, 2021). "Captoprilis is an angiotensin-converting enzyme (ACE) inhibitor, which is known to activate ACE2 that is the receptor that SARS-CoV-2 uses to infect human cells, suggesting that this drug might have negative effects for COVID-19 therapy." (PMID 34812273, 2021). "Further study is also required to verify the hypothesis of ACE being a secondary receptor for SARS-CoV in the absence of ACE2 and the possible effects in the incidence of respiratory distress in SARS compared with COVID-19." (PMID 32941612, 2021).
myocardial infarction (422 papers, 2001 to 2026). Gross necrosis of the myocardium, as a result of interruption of the blood supply to the area, as in coronary thrombosis. "Acute myocardial infarction, chronic heart failure, and medications like ACE inhibitors/ARBs and calcium channel blockers increased risk, suggesting COVID-19 interaction with cardiometabolic conditions worsens autonomic dysfunction." (PMID 41560500, 2026). "Increased ACE activity has been noted in neointima following experimental artery injury, and a rise in ACE expression is associated with an elevated risk of myocardial infarction." (PMID 40520007, 2025). "Further, increased serum ACE activity and peak of cardiac troponin 1 levels, a biomarker of tissue injury, have been associated with the +1166 CC genotype in patients with acute myocardial infarction." (PMID 39591456, 2024). "For example, in myocardial infarction patients, the ACE ID/DD genotype was independently associated with high IL-6 and kallikrein, a protease that plays a significant role in initiating and maintaining systemic inflammatory responses." (PMID 37238156, 2023). "ACE inhibitors and ARBs have similar BP-lowering efficacy, but there are no individual trial data or meta-analyses to show that ARBs reduce the risk of myocardial infarction or all-cause mortality." (PMID 34533690, 2023). "This study aimed to investigate the association between ACE I/D genotypes and the severity of coronary artery disease in patients with acute myocardial infarction." (PMID 37206099, 2023). "The prognostic role of the angiotensin-converting enzyme (ACE) insertion/deletion (I/D) genetic polymorphism in patients with acute myocardial infarction (AMI) is controversial and inconsistent across various study populations." (PMID 37657040, 2023). "The DD genotype of the ACE I/D polymorphism was associated with the severity of coronary artery disease in Vietnamese patients diagnosed with first acute myocardial infarction." (PMID 37206099, 2023). "In the EPHESUS study elprenone, the blocker of MR, was used in complex with ACE inhibitors and other components of standard therapy 3 to 14 days post-myocardial infarction associated with left ventricular dysfunction and congestive heart failure." (PMID 34206708, 2021). "For myocardial infarction, ACE inhibitors, DH CCBs, and β-blockers were associated with 20% to 28% relative risk reductions." (PMID 32083689, 2020). "The authors suggested that the ACE D allele was an independent risk factor for myocardial infarction in European." (PMID 33041838, 2020). "The greatest reductions in myocardial infarction risk were associated with ACE inhibitors, and DH CCBs and diuretics were associated with similarly significant reductions in the risk of stroke." (PMID 32083689, 2020). "In a previous study, the frequency of ACE D allele in myocardial infarction subjects has been shown to be significantly higher than in healthy control subjects." (PMID 33041838, 2020). "First observation was made for myocardial infarction in a landmark European multicenter study where the subjects homozygote for the ACE D allele, the allele which is associated with higher ACE levels, were found to be at increased risk." (PMID 31316987, 2019). "Genotyping of ACE gene polymorphisms has provided a genetic marker for several human heart diseases such as ischemic heart disease, coronary artery stenosis, myocardial infarction and ischemic cerebrovascular disease 9,10." (PMID 30800252, 2019). "Our case–control study aimed to access the potential association of insertion/deletion (I/D) ACE (angiotensin converting enzyme) gene polymorphism with myocardial infarction (MI) risk of occurrence among a sample of Moroccan patients, especially young ones." (PMID 29268798, 2017). "Higher risk of cardiovascular mortality was associated with increasing age, prescriptions for ACE inhibitor, and diagnosis of myocardial infarction or angina as compared with the other diagnoses." (PMID 26493455, 2015).
myocardial infarction (continued). "A polymorphism resulting from the insertion (Ins)/deletion(Del) of 287 nucleotides in intron 16 of the ACE gene has been extensively studied in relation to the risk of myocardial infarction." (PMID 25973747, 2015). "For the first time we confirmed definitely that the level of ACE activity is influenced by I/D polymorphism also in acute stage of myocardial infarction." (PMID 21162760, 2010). "The putative genetic association of the ACE I/D polymorphism with myocardial infarction is a salutary case in this regard." (PMID 19397801, 2009). "ACE inhibitors (lisinopril, enalapril, perindopril, ramipril) mediated nephropathy-myocardial infarction associations, suggesting class-wide effects despite ACEs’ widespread use in nephropathy and reported myocardial infarction risks." (PMID 41385310, 2026). "There is evidence that, to some extent, susceptibility to the myocardial infarction and coronary artery disease may be determined by the specific polymorphism of the ACE genotype." (PMID 38279313, 2024). "Further, the ACE D allele may be a risk factor for the development of HF with left ventricular dysfunction after myocardial infarction." (PMID 39591456, 2024). "Deletion polymorphism in the gene for ACE is a potent risk factor for myocardial infarction." (PMID 36435742, 2022). "The results of EUROPE (efficacy of perindopril in reduction of cardiovascular events among patients with stable coronary artery disease) and the HOPE (Heart Out- comes Prevention Evaluation) trials contribute to the decreased risk of myocardial infarction with ACE inhibitors." (PMID 34206708, 2021). "On the other hand, other studies showed that carriers of the ACE D polymorphism had a higher risk of myocardial infarction, and the ACTN3 X allele was associated with a higher risk of developing insulin resistance, which is a known factor of increased mortality." (PMID 32872456, 2020). "Both ACE inhibitors (OR 0.77; 95% CrI 0.62–0.92; moderate confidence) and ARBs (0.82; 95% CrI 0.67–0.98; moderate confidence) were associated with reduced risk of myocardial infarction compared with placebo." (PMID 26954482, 2016). "Moreover, 75% of patients with myocardial infarction or stroke were associated with at least one omission regarding use of aspirin, statin or ACE inhibitor, where indicated." (PMID 24763332, 2014). "Using the linkage-segregation analysis of the plasma ACE, Cambien has shown that the ACE I/D polymorphism was a marker for an unknown functional polymorphism (ACE S/s) which appeared to be a new independent risk factor for myocardial infarction." (PMID 25587546, 2014). "However, different populations apparently responded differently with regard to the appearance and overall impact of the ACE polymorphism on myocardial infarction." (PMID 20444272, 2010). "It has been reported that ACE DD polymorphism is a potent risk factor for myocardial infarction." (PMID 20444272, 2010). "For the first time we confirmed definitely that the level of ACE activity is influenced by I/D polymorphism in acute stage of myocardial infarction, although only small part of ACE activity variability may be explained by this polymorphism." (PMID 21162760, 2010). "In Morocco, this is the first case–control study investigating the potential correlation between I/D ACE gene polymorphism and susceptibility to myocardial infarction (MI)." (PMID 29268798, 2017). "As the ACE I/D polymorphism is partially associated with the plasma ACE level, the ACE DD genotype increases the plasma ACE concentration and the risk for numerous cardiovascular-renal diseased states, such as myocardial infarction, cardiomyopathy, IgA nephropathy, and diabetic nephropathy." (PMID 28352369, 2010). "Income‐related inequities persist in the initiation of evidence‐based pharmacologic therapies (e.g., ACE‐inhibitors, beta‐blockers, statins) for acute myocardial infarction, particularly among male patients." (PMID 40959183, 2025).
myocardial infarction (continued). "The administration of the ACE inhibitor (enalaprilat) in a porcine model of myocardial infarction significantly reduced the area of necrosis and reduced regional cell motion." (PMID 38279313, 2024). "CCBs can also be useful after myocardial infarction (MI); however, certain criteria including a prior attempt with combinatorial therapy of a beta blocker and an angiotensin-converting enzyme (ACE) inhibitor should be met before proceeding." (PMID 38255639, 2023). "Support for a polypill approach Effects of a secondary prevention combination therapy with an aspirin, an ACE inhibitor and a statin on 1-year mortality of patients with acute myocardial infarction treated with a beta-blocker." (PMID 37227456, 2023). "Overall, ACE-inhibitors/angiotensin-receptor blocker as well as betablockersshould be early initiated in the acute setting of acute myocardial infarction." (PMID 39077412, 2023). "Prevention of remodeling is currently significantly improved by early revascularization techniques for myocardial infarction, as well as early prescription of ARBs, ACE inhibitors and anti-aldosterones." (PMID 35386778, 2022). "This study showed an increase in myocardial infarction, stroke, and death among the black hypertensive patients taking ACE inhibitors compared with the patients who took CCB, thiazide diuretics, or beta-blockers." (PMID 36430371, 2022). "The patient was admitted to the pediatric intensive care unit with a differential diagnosis of acute myocardial infarction or acute myocardial injury related to cardiomyopathy and commenced on an ACE (angiotensin-converting enzyme) inhibitor." (PMID 35747106, 2022). "Most of them were on beta blockers, statins and ACE-inhibitors, and most had a history of myocardial infarction (MI)." (PMID 35054071, 2022). "The angiotensin-converting enzyme polymorphism gene had revealed a strong association with ACE activity, premature atherosclerosis, and myocardial infarction." (PMID 35741131, 2022). "There was a strong association between angiotensin-converting enzyme (ACE) gene polymorphism and several cardiovascular diseases, such as myocardial infarction, left ventricular hypertrophy, and restenosis after percutaneous transluminal coronary angioplasty." (PMID 35741131, 2022). "More specifically, the DD genotype of the ACE I/D polymorphism has been associated to higher levels of serum ACE and higher levels of circulating IL6 in patients with myocardial infarction." (PMID 34489863, 2021). "Blocking the RAAS by ACE inhibition after myocardial infarction has been shown to improve the fibrinolytic balance." (PMID 34220496, 2021). "Systematic reviews and meta-analyses of trials involving ARBs have shown that ARBs are inferior to angiotensin-converting enzyme (ACE) inhibitors in preventing myocardial infarction and mortality." (PMID 34257706, 2021). "To address this problem, we performed an analysis related to HRV after excluding patients with the comorbidity of myocardial infarction or the use of ACE and AT II inhibitors." (PMID 33329309, 2020). "Patients with LVGLS > − 14% were more symptomatic in terms of NYHA class, more comorbid (Eurolog II score, COPD and previous myocardial infarction) and received more medication (ACE-inhibitors, calcium antagonists and beta-blockers)." (PMID 33267772, 2020). "There were significant differences in the proportion of myocardial infarction comorbidity and the use of ACE and AT II inhibitors." (PMID 33329309, 2020). "In the present study, we demonstrate that the impact on neuroinflammation of ACE inhibitor therapy after myocardial infarction requires acute application and is directly related to the severity of inflammatory activity in the heart." (PMID 32125488, 2020). "Compared with other antihypertension medications, ACE inhibitors appeared to be the medications of choice to prevent myocardial infarction, and diuretics appeared to be the optimal choice to reduce revascularization." (PMID 32083689, 2020).
myocardial infarction (continued). "In myocardial infarction (MI)-induced HF models, comparative treatments with ACE inhibitor, aliskiren, or a combination of both revealed that the synergism of the drug combination was more beneficial than when either agent was used alone." (PMID 31261774, 2019). "Considering the importance of the over-activation of XO in presence of hyperuricemia, we investigated the effects of the concomitant andministration of XO inhibitors and ACE-inhibitors in post-acute myocardial infarction (AMI) patients." (PMID 29866077, 2018). "In myocardial infarction produced by ischemia/reperfusion, kinins help reduce infarct size following preconditioning or treatment with angiotensin‐converting enzyme (ACE) inhibitors (Rhaleb, Yang, & Carretero, 2011)." (PMID 28828213, 2017). "The use of ACE and chymase inhibitors in the treatment of myocardial infarction however needs to be further evaluated at pre-clinical and clinical levels." (PMID 27814397, 2016). "Treatment of acute myocardial infarction with ACE-inhibitor costs the least at US$2.4 million annually." (PMID 27524939, 2016). "In this sense, others reports show increased ACE2 activity in myocardial infarction and cardiac remodeling as a counter-regulatory mechanism that attempts to limit the adverse effects of elevated cardiac Ang II by ACE." (PMID 26010093, 2015). "After myocardial infarction and in diabetic nephropathy kinin receptors contribute to the protective effect of ACE inhibitors." (PMID 25369284, 2014). "the SMILE studies proved the prognostic benefit of zofenopril vs. placebo or other ACE-inhibitors (ACEIs) in post-acute myocardial infarction (AMI)." (PMID 25364906, 2014). "The biggest contributions came from secondary prevention following Acute Myocardial Infarction (95, (minimum 30, maximum 225), with ACE inhibitors, Beta blockers, statins, warfarin and aspirin being the main contributors in this group." (PMID 23658808, 2013). "A significant activation of the RAAS occurs after myocardial infarction, leading to a marked increase in Angiotensin-II generation by ACE, which promotes fibrosis and marked adverse LV remodeling." (PMID 23630610, 2013). "A recent German study on drug therapy after myocardial infarction revealed that 82% of the patients received β-blockers, 73% statins and 69% ACE inhibitors." (PMID 28352428, 2013). "This study demonstrated that the ACE DD genotype is an independent risk factor for ACS, and in particular, for acute myocardial infarction." (PMID 22333273, 2012). "These two actions make ACE inhibition a chief target in the treatment of hypertension, myocardial infarction (MI), heart failure, and type I diabetic nephropathy." (PMID 23131076, 2012). "Their study included 610 patients and 733 controls, and they observed that the ACE DD genotype occurred significantly more frequently in the male patients with myocardial infarction than in the controls." (PMID 24744648, 2012). "Data for the myocardial infarction four drugs indicator (Aspirin, Betablocker, Statin and ACE inhibitor) showed low levels of achievement at baseline, making it a good candidate for evidence based quality improvement and therefore financial incentivization." (PMID 21831317, 2011). "We evaluated the associations among angiotensin-converting enzyme (ACE) gene insertion/deletion (I/D) polymorphism, ACE activity and post-myocardial infarction (MI) left ventricular dysfunction and acute heart failure (AHF) early after presentation with MI with ST-segment elevation (STEMI)." (PMID 21162760, 2010). "Medical treatment with clopidogrel, ACE-inhibitors and statins also differed between quartiles, which reflect differences in age of the patients and type of myocardial infarction." (PMID 19583836, 2009).